LAMTOR5 (late endosomal/lysosomal adaptor, MAPK and MTOR activator 5)
Description:
As part of the Ragulator complex it is involved in amino acid sensing and activation of mTORC1, a signaling complex promoting cell growth in response to growth factors, energy levels, and amino acids. Activated by amino acids through a mechanism involving the lysosomal V-ATPase, the Ragulator plays a dual role for the small GTPases Rag (RagA/RRAGA, RagB/RRAGB, RagC/RRAGC and/or RagD/RRAGD): it (1) acts as a guanine nucleotide exchange factor (GEF), activating the small GTPases Rag and (2) mediates recruitment of Rag GTPases to the lysosome membrane. Activated Ragulator and Rag GTPases function as a scaffold recruiting mTORC1 to lysosomes where it is in turn activated. When complexed to BIRC5, interferes with apoptosome assembly, preventing recruitment of pro-caspase-9 to oligomerized APAF1, thereby selectively suppressing apoptosis initiated via the mitochondrial/cytochrome c pathway.
Synonyms: HBXIP; XIP; MGC71071
Tractability: Small molecule: a structure with a bound ligand is known. PROTAC: its protein half-life has been measured.
Gene: Protein-coding gene on chromosome 1 (110,401,249 to 110,407,942, reverse strand). Ensembl gene ENSG00000134248.
Subcellular location: Lysosome; Cytoplasm, cytosol
Subcellular location (Human Protein Atlas): Cytosol
Pathways (Reactome):
Signal Transduction: Energy dependent regulation of mTOR by LKB1-AMPK; MTOR signalling; Regulation of PTEN gene transcription; mTORC1-mediated signalling
Autophagy: Macroautophagy
Cellular responses to stimuli: Amino acids regulate mTORC1
Gene Ontology:
Molecular function: guanyl-nucleotide exchange factor activity; molecular adaptor activity; protein binding
Biological process: cellular response to amino acid stimulus; cellular response to nutrient levels; negative regulation of apoptotic process; positive regulation of canonical NF-kappaB signal transduction; positive regulation of gene expression; positive regulation of interleukin-8 production; positive regulation of protein localization to nucleus; positive regulation of TOR signaling; positive regulation of TORC1 signaling; protein localization to lysosome; regulation of cell size; response to virus; TORC1 signaling; viral genome replication
Cellular component: cytosol; FNIP-folliculin RagC/D GAP; lysosomal membrane; lysosome; protein-containing complex; Ragulator complex; late endosome membrane; cytoplasm
Genetic constraint (gnomAD): Loss-of-function variants: 7 observed, 9.05 expected, observed/expected ratio (o/e) 0.77, 90% interval 0.44 to 1.44. That is too few expected variants to judge how well the gene tolerates losing a copy. Missense variants: 83 observed, 93.48 expected, observed/expected ratio (o/e) 0.89, 90% interval 0.74 to 1.07. Synonymous variants: 30 observed, 35.41 expected, observed/expected ratio (o/e) 0.85, 90% interval 0.63 to 1.15.
Homologues: Orthologues: dog LAMTOR5 (100% identical), macaque LAMTOR5 (100% identical), pig LAMTOR5 (100% identical), guinea pig LAMTOR5 (99% identical), mouse Lamtor5 (99% identical), rat Lamtor5 (99% identical), zebrafish lamtor5 (75% identical), tropical clawed frog lamtor5 (71% identical), Drosophila melanogaster Lamtor5 (34% identical).
Diseases named in the same sentence as LAMTOR5 in open-access papers:
LAMTOR5 is named in the same sentence as 37 diseases in open-access papers, as found by Europe PMC text mining. Sharing a sentence is not in itself a finding about the gene and the disease. The quoted sentences say what the papers report.
breast carcinoma (72 papers, 2012 to 2025). "HBXIP (LAMTOR5) plays an important role in the promotion of proliferation of breast cancer cells." (PMID 29416623, 2018).
liver cancer (6 papers, 2014 to 2023). An epithelial or non-epithelial malignant neoplasm that arises from the liver. "Furthermore, the hepatitis B X-interacting protein, HBXIP, also termed late endosomal/lysosomal adaptor, MAPK and mTOR activator 5 (LAMTOR5), was claimed to induce the upregulation of glucose transporter 1 (GLUT1) through the NF-κB pathway during hepatic cancer development." (PMID 36902395, 2023).
systemic lupus erythematosus (2 papers, 2024 to 2025). An autoimmune multi-organ disease typically associated with vasculopathy and autoantibody production. "Here it is demonstrated that Lamtor5 level is markedly decreased in peripheral blood mononuclear cells (PBMCs) of patients with systemic lupus erythematosus (SLE)." (PMID 38639386, 2024).
dysferlinopathy (1 paper, 2023). "Analysis of muscle transcripts from patients with dysferlinopathy helped identify the following 7 upregulated DEGs involved in the cellular response to stress: HSPA9, RPTOR, MTOR, LAMTOR1, LAMTOR5, ATP6V0D1, and ATP6V0B." (PMID 38125829, 2023).
prostate carcinoma (1 paper, 2022). A carcinoma that arises from epithelial cells of the prostate gland. "Interestingly, we found high expression of antioxidant genes; SOD1, TXN, LAMTOR5, and ATOX1 in prostate cancer patients having higher ERG fusion expression." (PMID 35508713, 2022).
cancer (22 papers, 2014 to 2025). A tumor composed of atypical neoplastic, often pleomorphic cells that invade other tissues. "Hepatitis B X-interacting protein (HBXIP, also termed as LAMTOR5) plays a crucial role in regulation of cancer progression, while the mechanism is still unclear." (PMID 29416623, 2018). "Studies had demonstrated that HBXIP (LAMTOR5) expression was up-regulated in many types of cancers." (PMID 29416623, 2018). "Particularly, the key regulators of mTOR signaling such as LAMTOR2, LAMTOR5, YWHAB, LAMTOR1, FKBP1A, and RHEB were also upregulated in the cancer cells of intra‐tumoral TLS‐low group." (PMID 38498682, 2024). "Heterozygous amplifications and deletions are the main types of copy number variations in molecular VM-related DEGs in pan-cancer, among which the copy numbers of NTN1, SIPR1, LAMTOR5, and ZRANB2 are heterozygous deletions in most tumors." (PMID 37197406, 2023).
infection (4 papers, 2021 to 2025). The state of being infected such as from the introduction of a foreign agent such as serum, vaccine, antigenic substance or organism. "Furthermore, there were nine proteins that were specifically detected at 7 days post-infection (Saa2, Trappc1, Cxadr, Armc8, Hbxip; Lamtor5, Prppsap2, Usp46, Pcdh10, Neo1)." (PMID 36061859, 2022).
immune dysfunctions of (1 paper, 2023). "Here, the upregulation of CDC42 and LAMTOR5 expression may be correlated with immune dysfunctions of the airways caused by ammonia exposure." (PMID 37250049, 2023).
LAMTOR5 also shares sentences with these, for which no sentence is quoted: tumor (38 papers); hepatoma (9); gastric cancer (5); breast tumor (3); cervical cancer (2); Hepatitis (2); Hepatitis B (2); lung carcinoma (2); lymph node metastases (2); ovarian carcinoma (2); Ascites (1); bladder urothelial carcinoma (1); breast (1); breast invasive carcinoma (1); colonic carcinoma (1); colorectal cancer (1); COVID-19 (1); diabetic cardiomyopathy (1); dilated cardiomyopathy (1); endometrioid adenocarcinoma (1); esophageal squamous cell carcinoma (1); gastric tumors (1); granulosa cell tumor (1); Hepatic steatosis (1); hypothyroidism (1); mucinous adenocarcinoma (1); non-small cell lung carcinoma (1); oligodendroglioma (1); serous carcinoma (1).